NR3C1 (nuclear receptor subfamily 3 group C member 1)
Diseases named in the same sentence as NR3C1 in open-access papers (continued):
Sharing a sentence is not in itself a finding about the gene and the disease.
chronic asthma (1 paper, 2022). An asthma that is characterized by the development of persistent airway inflammation and recurrent attacks of breathlessness and wheezing, which vary in severity and frequency. "Deficiency of NR3C1 causes cortisol to act in an uncontrolled manner leading to chronic asthma." (PMID 35270342, 2022).
Dental anxiety (1 paper, 2021). "We were unable to find any statistically significant findings between pain catastrophising, A‐State, A‐Trait, Dental anxiety scores or SNPs of the COMT, NR3C1 and HTR2A genes and participants self‐reported pain levels during orthodontic treatment." (PMID 34273191, 2021).
dental caries (1 paper, 2025). The decay of a tooth, in which it becomes softened, discolored, and/or porous. "Furthermore, CCND1 also demonstrated a significant association with the progression of dental caries (odds ratio = 1.15564, 95% CI 1.05554-1.26523, p = 0.0018), while SLC6A4, CASP3, NR3C1, and ANXA1 were linked to diseases of the pulp and periapical tissues." (PMID 41023518, 2025).
emphysema (1 paper, 2025). "However, whether NR3C1+ CD4 T cells are protective or pathogenic in human emphysema and COPD merits further investigation in experimental and clinical studies (Graphic Abstract)." (PMID 40993192, 2025).
glomerulonephritis (1 paper, 2022). A renal disorder characterized by damage in the glomeruli. "Therefore, NR3C1 and other related gene polymorphisms on CS responsiveness in other diseases apply to IgAV glomerulonephritis, which still needs further research to confirm its universality." (PMID 35935867, 2022).
Graves’ orbitopathy (1 paper, 2023). "To investigate the relationship between NR3C1 SNPs, GD susceptibility, and clinical features, we studied 792 individuals, including 384 patients, among which 209 presented with Graves’ orbitopathy (GO), and 408 paired healthy controls." (PMID 37189773, 2023).
Headache (1 paper, 2022). Cephalgia, or pain sensed in various parts of the head, not confined to the area of distribution of any nerve. "GRIA2 and NR3C1, involved in glutamate and glucocorticoid signalling, respectively, appear to be specific to the headache phase in our data set." (PMID 36050647, 2022).
herpesvirus infection (1 paper, 2019). "We demonstrate a tight regulation of nr3c1 during the differentiation of CD8+ T cells during herpesvirus infection." (PMID 31354707, 2019). "Both α- (HSV1) and γ- (MHV68) herpesvirus infection expanded CD8+ T cells down regulated their nr3c1 expression in the acute phase of response but memory cells regained the expression." (PMID 31354707, 2019). "Both α-(HSV1) and γ-(MHV68) herpesvirus infection expanded CD8+ T cells down regulated nr3c1 indicating corticosteroid-mediated effects were not limited to one pathogen or the specific clonotype." (PMID 31354707, 2019).
hyperhomocysteinemia (1 paper, 2014). A serious metabolic condition caused by mutations in the MTHFR gene, medications, or nutritional deficiency. "Indeed, minor diet-induced DNA methylation changes of 3–6% of the NR3C1 gene have been linked to hyperhomocysteinemia in cardiovascular disease." (PMID 24763279, 2014).
idiopathic pulmonary fibrosis (1 paper, 2024). Idiopathic pulmonary fibrosis (IPF) is a nonneoplastic pulmonary disease that is characterized by the formation of scar tissue within the lungs in the absence of any known cause. "Interestingly, we also have identified significant DEG-enrichments of target gene sets for five TFs, TCF12, ZEB1, NR3C1, TEAD4 and JUN, which were previously reported to be the regulators in idiopathic pulmonary fibrosis." (PMID 39103936, 2024).
ischemia (1 paper, 2022). A hypoperfusion of the BLOOD through an organ or tissue caused by a PATHOLOGIC CONSTRICTION or obstruction of its BLOOD VESSELS, or an absence of BLOOD CIRCULATION. "From them all, the CCCTC-binding factor (CTCF), the glucocorticoid receptor (NR3C1), and the nuclear respiratory factor 1 (NRF1) were connected to nodes exhibiting opposite regulation at revascularization and post-conditioning versus ischemia." (PMID 35216205, 2022).
juvenile idiopathic arthritis (1 paper, 2011). Juvenile idiopathic arthritis (JIA) is the term used to describe a group of inflammatory articular disorders of unknown cause that begin before the age of 16 and last over 6 weeks. "The glucocorticoid receptor gene (NR3C1) has been suggested as a candidate gene affecting juvenile idiopathic arthritis (JIA) course and prognosis." (PMID 21232135, 2011).
leiomyoma (1 paper, 2023). A well-circumscribed benign smooth muscle neoplasm characterized by the presence of spindle cells with cigar-shaped nuclei, interlacing fascicles, and a whorled pattern. "The involvement of many proteins such as FN1, COL1A1, BMP7, CCND1, EZH2, HMGA2, AhR, and E2F1 shown in the protein–protein interaction networks are well known in leiomyoma pathogenesis; others, such as SOX2, REN, PPARG, ABCB1, and NR3C1 are novel and require further investigation." (PMID 36835153, 2023).
liver diseases (1 paper, 2014). "NR3C1 is part of the NR superfamily of TFs that are known to play a role in the development and adaptations of liver diseases." (PMID 25399255, 2014).
nicotine addiction (1 paper, 2023). "NR3C1 methylation was slightly higher in patients with nicotine addiction compared to controls, but the difference was not significant between the two groups (% 95.33 vs. 91.08, p = 0.269)." (PMID 36982343, 2023).
Nutritional Disease (1 paper, 2020). "Another gene network identified by IPA in the D2FAST48h vs. D3REFED24h contrast focused on the GCR (NR3C1) and was functionally annotated as “Nutritional Disease”." (PMID 32005146, 2020).
Pan (1 paper, 2024). "TCGA’s Pan Cancer Atlas data indicated that several cancers present negative correlation between FOXA1 and NR3C1 transcript levels." (PMID 38015476, 2024).
pseudohypoaldosteronism (1 paper, 2019). An inherited or acquired disorder of electrolyte metabolism, characterized by the inability of the renal tubules to respond to aldosterone. "This lack of response to mineralocorticoids was reminiscent of pseudohypoaldosteronism in humans and could not be explained by a decrease in mRNA expression of NR3C1 or NR3C2 in rice rat cultures." (PMID 31491720, 2019).
psychosomatic disorders (1 paper, 2025). "This review first outlines how epigenetic dysregulation contributes to psychosomatic disorders through altered expression of genes such as GRM2, TRPA1, SLC6A4, NR3C1, leptin, BDNF, NAT15, HDAC4, PRKCA, RTN1, PRKG1, and HDAC7." (PMID 41439979, 2025).
pulmonary sarcoidosis (1 paper, 2021). Sarcoidosis affecting the lung parenchyma. "To validate the expression of VEGFA and NR3C1, we performed IHC to examine 12 mediastinal lymph node tissues from pulmonary sarcoidosis patients and 13 mediastinal lymph node tissues from tuberculosis patients." (PMID 34055877, 2021).
sarcoidosis (1 paper, 2021). Sarcoidosis is a multisystemic disorder of unknown cause characterized by the formation of immune granulomas in involved organs. "From our results, we found that VEGFA and NR3C1 were overexpressed in the pathological tissue of sarcoidosis, which was mainly regulated by hsa-miR-126." (PMID 34055877, 2021). "In this study, NR3C1 was upregulated in sarcoidosis and expressed in pathological specimens, which may be related to the sensitivity of sarcoidosis to glucocorticoid therapy." (PMID 34055877, 2021). "In sarcoidosis pathological tissue, hsa-miR-126 was highly expressed, and VEGFA and NR3C1 were overexpressed." (PMID 34055877, 2021). "Among the identified miRNAs involved in sarcoidosis, hsa-miR-126 was highly expressed, and the two target genes VEGFA and NR3C1 were also highly expressed in lymph node samples of sarcoidosis." (PMID 34055877, 2021). "Simultaneously, we found that NR3C1 is not always highly expressed, which may be related to the insensitivity of some sarcoidosis patients to glucocorticoid treatment in clinical practice." (PMID 34055877, 2021).
Seizure (1 paper, 2023). A seizure is an intermittent abnormality of nervous system physiology characterized by a transient occurrence of signs and/or symptoms due to abnormal excessive or synchronous neuronal activity in the brain. "We investigated the association between the glucocorticoid receptor (GR) gene, also known as the nuclear receptor subfamily 3, group C, member 1 (NR3C1), rs41423247 polymorphism, and functional seizures (psychogenic nonepileptic seizures/attacks) in a case–control study." (PMID 37593891, 2023).
sexual dysfunction (1 paper, 2019). Disturbances in sexual desire and the psychophysiologic changes that characterize the sexual response cycle and cause marked distress and interpersonal difficulty.
Shock (1 paper, 2025). The state in which profound and widespread reduction of effective tissue perfusion leads first to reversible, and then if prolonged, to irreversible cellular injury. "Cortisol binds two receptors, the glucocorticoid (GR, NR3C1) and mineralocorticoid receptor (NR3C2), however, the GR is more relevant in responses to stress, sepsis and septic shock, and as such, the focus of this review." (PMID 39968295, 2025).
Turner syndrome (1 paper, 2017). Turner syndrome is a chromosomal disorder associated with the complete or partial absence of an X chromosome. "Eight TFs and four ERFs are among the differentially expressed genes, as well as eight genes associated with Turner syndrome (PROCR, NR3C1, INSR, APOB, BMP15, F8, IL6, and WAS) and two genes that are haploinsufficient in humans (RAD50 and SLC33A1)." (PMID 28818098, 2017).
tumor (157 papers, 2005 to 2026). "We observed the upregulation of genes associated with positive anti-tumor activity, including NR3C1, BRCA1, BRCA2 and SFN." (PMID 40043049, 2025). "Other reported mechanisms involving the receptor include lower overall NR3C1 gene expression which leads to decreased GCR expression and has been linked to poor prognosis and tumor development." (PMID 38867099, 2024). "Given that all nucleated cells express GR (encoded by Nr3c1), tumor cells would be the predicted targets of tumor cell–derived glucocorticoids." (PMID 37471141, 2023). "NR3C1 (nuclear receptor subfamily 3 group C member 1) was implicated in HNSCC in a pan-cancer bioinformatics analysis involving 3000 tumours." (PMID 35326543, 2022). "The SB insertion pattern observed in Nr3c1, the gene that encodes the glucocorticoid receptor, is suggestive of its role as a tumor suppressor." (PMID 31338332, 2019). "The oriented release of NR3C1 inhibitor inside the tumor may also solve concerns regarding tumor chemoresistance caused by steroid administration." (PMID 39731339, 2025). "Upregulation of NR3C1 in certain tumors might cause oncogenes to become active or alter the tumor microenvironment to encourage the migration and multiplication of cancer cells." (PMID 40406148, 2025). "MiR-1270 expression in tumor samples was inversely associated with NR3C1 expression." (PMID 36797317, 2023). "NR3C1 is revealed to be associated with the failure of checkpoint blockade, and the loss of NR3C1 potentiates the response to checkpoint blockade, suggesting inhibiting NR3C1 is a potential strategy to improve anti-tumor immune responses in combination with other treatments." (PMID 38002057, 2023). "Single‐cell transcriptomic analysis indicates that this reprogramming correlates with elevated glucocorticoid receptor (GR/NR3C1) pathway activity in tumor‐infiltrating NK cells." (PMID 41082397, 2026). "UMAP clustering identified different triple-negative tumour cell clusters which were characterized by migration and GR signature and by NR3C1, and GR target SGK1 and TSC22D3 gene expression." (PMID 39905197, 2025). "Concurrently, genes that are associated with antigen processing and presentation were diminished in NR3C1+ DCs in TNBC tumours." (PMID 40287432, 2025). "The NR3C1 gene ontology was hypomethylated in all four portions of the stomach, and the tumor group had higher methylation levels than the control group in all four portions of the stomach." (PMID 40995432, 2025). "Our comprehensive scRNA-seq analysis of tumour-infiltrating immune cells from TNBC patients highlighted NR3C1 as the dominant steroid receptor gene, a finding that is consistent with data from our TNBC mouse model." (PMID 40287432, 2025). "Analysis using the GEPIA database revealed a significant positive correlation between TGM2 and NR3C1 expression in both normal and tumor tissues (R = 0.53, P = 7.6×10−60)." (PMID 41050683, 2025). "These glucocorticoids are locally produced by tumor-associated monocyte-macrophage cell lines, and the impact of GC on CD8+ T cells is contingent upon NR3C1." (PMID 40959664, 2025). "The transcriptional regulation effects of NR3C1 on tumor progression remain worthy of further investigation." (PMID 40740652, 2025). "The analysis revealed the glucocorticoid receptor NR3C1 as the highly expressed steroid hormone receptor gene in TNBC tumours." (PMID 40287432, 2025). "We also identified genes encoding membrane receptors (IL7R, OSMR, EGFR) and transcriptional regulators (BNC2, BNC1, HMGA2, KLF7, NR3C1) as enriched in Basal tumours." (PMID 36944729, 2023). "Expression of NR3C1 was verified by various tumor databases and assessed using RT-qPCR and western blot." (PMID 37807060, 2023). "The results showed that knockdown of NR3C1 significantly slowed tumor growth in nude mice, with a final tumor weight of only about 40% of that in the control group (P < 0.05)." (PMID 37807060, 2023).
tumor (continued). "To investigate the expression level of NR3C1 in ccRCC, we first searched the The Cancer Genome Atlas (TCGA) and Clinical Proteomic Tumor Analysis Consortium (CPTAC) databases." (PMID 37807060, 2023). "Protein Atlas verified that APOE, MIF, and NR3C1 were expressed in tumor tissues at different levels." (PMID 36452480, 2022). "The low expression levels of NR3C1 (HR = 0.397, p < 0.05) were remarkably associated with the poorer BCSS of patients with tumor pathological stages I–II." (PMID 35317079, 2022). "According to the GEPIA website, PKM2 and ENC1 were over-expressed in tumor tissues and under-expressed in normal tissues, but NR3C1 was the inverse." (PMID 36531950, 2022). "Identification of FKBP4/NR3C1 axis as the novel NRF2 regulator would provide in-depth insights for immunological anti-tumor strategy to overcome BC." (PMID 35087512, 2021). "Identification of FKBP4/NR3C1/NRF2 axis would provide insights for novel anti-tumor strategy against BC among tumor microenvironment." (PMID 35087512, 2021). "We found that the glucocorticoid receptor Nr3c1 was expressed in all tumor-infiltrating immune cells." (PMID 32680985, 2020). "The expression of NR3C1 was found to be reduced in many tumor tissues owing to methylation of its promoter." (PMID 33221755, 2020). "Taken together, our discovery of Nr3c1 as a major DLBCL CIS and its strong association with therapy response/resistance establishes NR3C1 as a bona fide tumor suppressor and predictive marker in human DLBCL." (PMID 30926791, 2019). "IRF7 could regulate tumor microcirculation through the regulation of NR3C1 expression under some environments could promote tumor cell proliferation by regulating the tumor microenvironment." (PMID 40406148, 2025). "FOXA1 and NR3C1 are expressed at fluctuating degree between the different tumor types." (PMID 38015476, 2024). "We then assessed the effect of NR3C1 KD on PDAC tumor spheroids." (PMID 38877560, 2024). "From the PCR results of the risk-predictor genes, we speculated high expression levels of NR3C1 in tumor tissues and expressions of IL-6 and SRPX converged in paratumor tissues." (PMID 36675190, 2023). "Notably, the gene encoding GR (NR3C1) was among the genes significantly more expressed in SARC vs. UroCa samples in both the organoid and tumor sample cohorts (P < 0.0001, unpaired t test)." (PMID 37919480, 2023). "Importantly, we also identified a Basal TF network, including ZBED2, KLF7, HMGA2, and NR3C1 as major regulators, whose expression was restricted to the basal component of tumours, according to scRNA-seq data." (PMID 36944729, 2023). "Both control and Nr3c1-deficient B16 cells exhibited identical growth in vivo, demonstrating that tumor-derived glucocorticoids do not signal in an autocrine manner to promote growth." (PMID 37471141, 2023). "The expression of NR3C1 was low in tumor grade III as compared to grade II (p = 0.04)." (PMID 36430579, 2022). "Through study of the transcriptome of tumor-infiltrating CD8+ T cell subsets, we demonstrated that Nr3c1 (gene encoding glucocorticoid receptor; GR) is highly expressed by dysfunctional or exhausted CD8+ T cells, thus associating GR activity with suppressed CD8+ T cell responses." (PMID 36337733, 2022). "They examined 47 tumor samples and the CAL-1 cell line by various techniques (e.g., cytogenetics, a-CGH, FISH, targeted sequencing) and found that the loss of the glucocorticoid receptor gene, NR3C1, defined a high-risk group of patients." (PMID 31035408, 2019). "Additionally, tumour cells with higher NR3C1 expression displayed an increased migration signature." (PMID 39905197, 2025). "Importantly, based on our data for 7 Ba/Sq samples, we were able to identify higher enhancer activity associated with potential key genes in Basal tumour biology, including cell surface receptors (IL7R, OSMR, EGFR, MET) and transcriptional regulators (BNC2, HMGA2, KLF7, NR3C1)." (PMID 36944729, 2023).